IL22 (interleukin 22)
Diseases named in the same sentence as IL22 in open-access papers (continued):
Sharing a sentence is not in itself a finding about the gene and the disease.
breast cancer (continued). "We therefore examined whether IL-22 and/or S1P signaling would induce the migration of breast cancer cells using a Transwell assay." (PMID 31935914, 2020). "Taken together, these results indicate that IL-22 may serve as an important determinant of S1PR1 induction in breast cancer cells." (PMID 31935914, 2020). "Highly metastatic breast cancer cells expressed elevated protein levels of pERK and pSTAT3 compared to low metastatic breast cancer cells and IL-22R1 silencing led to reduced protein levels of pERK and pSTAT3 upon IL-22 exposure." (PMID 31935914, 2020). "Regulation of IL-22 in breast cancer still needs to be elucidated." (PMID 32649314, 2020). "Notably, our present results show that IL-22 signaling pathway significantly enhanced the invasive potential of breast cancer cells and increased MCP-1 production from MSCs, inducing macrophage accumulation." (PMID 31935914, 2020). "Our findings suggest a mechanism for how IL-22 regulates tumor growth in breast cancer, and indicate blocking IL-22 function might reduce IL-1β- and IL-23-induced tumor progression of breast cancer." (PMID 32649314, 2020). "Matrix metalloproteinase-2 (MMP-2) and MMP-9 have been suggested to promote the invasion of breast cancer cells and we thus reasoned that these factors could be mediators of the invasive potential of breast cancer cells through IL-22." (PMID 31935914, 2020). "We examined whether the IL-22 dependent induction of S1PR1 expression in MDA-MB231 breast cancer cells also occurs in macrophages." (PMID 31935914, 2020). "Our findings suggest blocking IL-22 function might reduce IL-1β- and IL-23-induced tumor progression of breast cancer." (PMID 32649314, 2020). "In breast cancer, elevated levels of IL‐22 are reported in serum and tumor tissues." (PMID 31725949, 2020). "The study shows that IL‐22 regulates the malignant transformation in cancer cells through EMT pathway that may further affect the invasion in breast cancer." (PMID 31725949, 2020). "However, the current understanding of the involvement of IL‐22 in breast cancer tumorigenesis is derived from the use of various human/mouse cancer cell line models." (PMID 31725949, 2020). "In addition, we observed that IL-22 promoted the invasive activity of breast cancer cells by inducing MMP-9 to facilitate the accumulation of macrophages, thereby providing an initial signal for cancer metastasis." (PMID 31935914, 2020). "The interleukin-22 (IL-22) signaling pathway is well known to be involved in the progression of various cancer types but its role in bone metastatic breast cancer remains unclear." (PMID 31935914, 2020). "Endogenous IL-22 might also exert proliferative effect in breast cancer, which can be confirmed by a test in IL-22 gene knock-out mice." (PMID 32649314, 2020). "However, other reports have shown that IL-22 inhibits proliferation and growth of tumor cells in a renal cell carcinoma line and a murine cell line of breast cancer." (PMID 31750252, 2019). "In current study, we determined the role of miR-486-5p, Dock1, and IL-22 in breast cancer EMT." (PMID 31528235, 2019). "However, in EMT6 breast cancer cells, IL-22 induces STAT3 phosphorylation, but reduced ERK1/2 and Akt phosphorylation." (PMID 25793261, 2015). "Moreover, IL-38 reduces the secretion of IL-23 in mice, and since ILC3 cells produce IL-22, IL-23, and other cytokines, their inhibition could reduce breast cancer development." (PMID 41596472, 2026). "For example, Th22 cells may facilitate metastasis in high-grade breast cancer via IL-22." (PMID 36142210, 2022). "Indeed, IL-22 promoted the proliferation of breast cancer cells in a STAT3-dependent manner." (PMID 36341381, 2022). "Moreover, IL-22 promoted the expression of pro-tumor HOXB-AS5 proteins in breast cancer." (PMID 34300224, 2021).
breast cancer (continued). "Given our current observations that both IL-22R1 and S1P1R expression is elevated in bone metastatic breast cancer, we investigated whether IL-22 stimulates the S1P signaling pathway in human bone marrow-derived mesenchymal stem cells (hBM-MSCs), which reside in the bone environment." (PMID 31935914, 2020). "Here, the increase in IL‐22 levels during the invasion stage could be due to increased presence of these cells in the TME as in the MMTV‐PyMT breast cancer model, leukocyte infiltration in breast tumor tissues occurs between the early carcinoma and late carcinoma stages." (PMID 31725949, 2020). "In breast cancer, it is not established whether elevated levels of IL‐22 are associated with a specific stage of disease progression." (PMID 31725949, 2020). "However, regulation of IL-22 in breast cancer still needs to be elucidated." (PMID 32649314, 2020). "We discovered that the number of metastatic tumor nodules in lung of mice was lower in the group with overexpression of miR-486-5p or downregulation of Dock1 under stimulation with IL-22, suggesting miR-486-5p could repress breast cancer cells metastasis in mice models." (PMID 31528235, 2019). "Additionally, a study has shown that IL-22 released by Th17 cells can activate the MAP3K8 signaling pathway in BC cells, which in turn activates the STAT3 and AP-1 pathways, thereby increasing breast cancer aggressiveness." (PMID 41597595, 2025). "IL-22 has also been described to mediate macrophage infiltration in the TME and the migration of breast cancer cells." (PMID 36588678, 2022). "Moreover, IL-22 is known to promote wound healing in the skin and gastrointestinal tract and has been shown to promote mouse mammary cancer growth, all suggesting that this cytokine may support a breast tumor microenvironment and provide aid for the growth of malignant cells." (PMID 36142210, 2022). "It seems that Th17 cells by creating inflammatory conditions through the secretion of cytokines, including IL-22, IL-17, TNF-α, IL-21, and IL-6, can significantly enhance breast cancer progression." (PMID 35248028, 2022). "Thus, a possible mechanism might be IL-1β and IL-23 promoting breast cancer progression via IL-22." (PMID 32649314, 2020). "In 4T1 breast cancer model, ILC3 was a major producer of IL-22, which was increased by giving IL-1β and IL-23." (PMID 32649314, 2020). "IL-22 increased phosphorylated STAT3 level and proliferation of breast cancer cells in vitro, an effect blocked by a STAT3-inhibitor stattic." (PMID 32649314, 2020). "We assessed the effect of giving IL-22 in tumor growth of mice inoculated with 4T1, MCF7 and MDA-MB-231 breast cancer cells." (PMID 32649314, 2020). "We illustrated that IL-22 and Dock1 promote the invasion, metastasis, and EMT of breast cancer using Transwell invasion assay, western blot and immunofluorescence." (PMID 31528235, 2019). "In summary, our study demonstrated that IL-22 and Dock1 promoted the invasion, metastasis, and EMT of breast cancer cells." (PMID 31528235, 2019). "To screen for lncRNAs that may potentially participate in the IL-22-IL-22R1 pathway during breast cancer progression, we treated MDA-MB-231 and MCF-7 cells with PBS (control) or IL-22, and detected expression changes of the top 20 upregulated lncRNAs in BC." (PMID 29262587, 2017). "A moderate negative correlation was observed between IL-21 and IL-22 serum levels in patients with benign breast lesions (rS = −0.663, p = 0.002), whereas no such correlation was found in patients diagnosed with breast cancer (rS = −0.109, p = 0.410)." (PMID 40729006, 2025). "The IL-22 stimulation of MSCs increased the invasive potential of MDA-MB231 cells which was suppressed by the S1P antagonist, again indicating that the IL-22 cytokine has a promoting effect on breast cancer cell migration and invasion via S1P signaling." (PMID 31935914, 2020).
breast cancer (continued). "In addition to the S1PR1 axis, IL-22 stimulated the expression of matrix metalloproteinase-9 (MMP-9), thereby promoting breast cancer cell invasion." (PMID 31935914, 2020). "Importantly, IL-22 stimuli promoted the expression of IL-22R1 and S1PR1 in aggressive MDA-MB-231 breast cancer cells." (PMID 31935914, 2020). "Hence, the results manifested that Dock1 increased mesenchymal properties of breast cancer cells and triggered EMT under stimulation of IL-22." (PMID 31528235, 2019). "Our study also analysed IL-22 serum concentrations in patients with invasive breast cancer, taking into account the molecular subtype and degree of tumour malignancy, as well as in patients with non-malignant breast cancer." (PMID 40729006, 2025). "However, dysregulation of IL-22 may contribute to the development of TNBC and the pathology in breast cancer." (PMID 36588678, 2022). "Additionally, the results demonstrated that IL-22 did not influence the level of miR-486-5p in breast cancer cells." (PMID 31528235, 2019). "IL-22 did not affect Dock1 protein levels in breast cancer cells." (PMID 31528235, 2019). "In addition, interleukin-22 (IL-22) phosphorylates Tpl2 through IL-22R1, activates the MEK-ERK, JNK, and STAT3 signaling pathways, and results in the epithelial-mesenchymal transition (EMT) through AP-1 in breast cancer." (PMID 25723737, 2015). "Although this previous study did not determine whether IL-22 activated STAT3 in breast cancer cells to reduce their sensitivity to NK cell-meditated cytotoxicity, solid evidences confirm that tumor cell-intrinsic STAT3 activation can impair NK cell antitumor immunity via intricate mechanisms." (PMID 38596684, 2024). "We showed giving IL-22 increased proliferation of breast cancer cells including estrogen receptor-positive MCF7 cells and triple-negative 4T1 and MDA-MB-231 cells, which indicates IL-22-mediated proliferative effect might not depend on expression of estrogen receptor." (PMID 32649314, 2020).
pneumonia (33 papers, 2015 to 2024). An acute, acute and chronic, or chronic inflammation focally or diffusely affecting the lung parenchyma, caused by an infection in one or both of the lungs (by bacteria, viruses, fungi, or mycoplasma.). "The resistance of neonatal mice to pneumonia is dependent on the recruitment of intestinal commensal bacteria-directed group 3 innate lymphoid cells into the lungs, which in turn mediate IL-22-dependent host defense against pneumonia." (PMID 38352055, 2024). "Studies have shown that IL-22 can reduce the severity of pneumonia through immune regulation and tissue-protective or regenerative functions." (PMID 39258622, 2024). "Both intestinal microorganisms and intestinal dendritic cells can improve the migration of ILC3 to the lungs by inducing the expression of CCR4 on the IL-22+ILC3, which eventually mediated IL-22-dependent host resistance to pneumonia in newborn mice." (PMID 37680747, 2023). "For example, the migration of IL-22-producing ILC3s to the lung is needed for protection against pneumonia, which is initiated by sensing commensal bacteria via intestinal DCs." (PMID 37630849, 2023). "Previous studies have shown that disruption of postnatal commensal colonization or selective loss of dendritic cells interrupts the IL-22 + ILC3 migratory program in the lung, rendering neonatal mice more susceptible to pneumonia." (PMID 38110878, 2023). "In a model of bleomycin-induced pneumonia, IL22 was shown to lose its protective effect and instead promoted airway inflammation in the presence of IL17A." (PMID 37189778, 2023). "The prognosis and progression of pneumonia are directly related to the high levels of interleukins IL-17 and IL-22 in the lungs." (PMID 37764047, 2023). "Although IL-22 does not appear to reduce virus titer during infections, studies have illustrated that IL-22 can reduce the pneumonia severity via the immune regulation and tissue protective or regenerative functions." (PMID 35967401, 2022). "IL-22-producing ILC3s are important both in the newbornhood and adulthood to control a S. pneumoniae infection and prevent pneumonia." (PMID 34659248, 2021). "The first description of a host defense role for IL-22 in the lung was demonstrated using the Klebsiella pneumoniae model of pneumonia." (PMID 32582219, 2020). "The group 3 ILCs activation to produce IL-22 during S. pneumoniae-induced pneumonia also involves the activation of pulmonary dendritic cells (DC)." (PMID 32849610, 2020). "The S. pneumoniae pneumonia frequently induces the group 3ILCs accumulation in the lungs, which produce IL-22 to protect against severe pneumonia." (PMID 32849610, 2020). "Although IL-22 played a large role in severity of pneumonia in our studies, the role of surfactants cannot be overlooked." (PMID 29720526, 2018). "During PA pneumonia, we observed a correlation between the levels of IL-22 in the lungs of infected mice and the histological damage observed." (PMID 28887540, 2017). "In this study, we showed a correlation between the protective role of IL-22 during PA pneumonia and PMN recruitment in the lungs." (PMID 28887540, 2017). "In this context of epithelium damage, we assessed the expression of the interleukin (IL)-22 during PA pneumonia." (PMID 28887540, 2017). "This is correlated with the transient increase of IL-22 protein levels in the lungs of infected mice 6 and 24 hours after the onset of pneumonia (p < 0.01) followed by a drop back to IL-22 basal levels at 48 hours (ns; p = 0.4 compared with the sham group)." (PMID 28887540, 2017). "We also investigated potential differences in IL-22 biology in the largest disease subgroup (pneumonia) by investigating possible correlations with IL-22 in BL from these patients." (PMID 27388918, 2016). "Our study detected higher levels of IL-22 in lavage samples from patients with pneumonia compared to controls, supporting the suggestion that IL-22 plays a role in the pulmonary response to infection." (PMID 27388918, 2016).
pneumonia (continued). "IL-22 seems to be protective in the acute phases of lung inflammation or injury such as pneumonia, fungal infection, traumatic lung injury, acute lung injury associated with pancreatitis or the initial phase of allergic airway inflammation." (PMID 27388918, 2016). "In lavage from patients with pneumonia, IL-22 concentrations were unrelated to total percentages of lymphocytes, macrophages, neutrophils, eosinophils and to the CD4 to CD8 T cell ratio (p = 0.5, 0.98, 0.86, 0.98, 0.65, respectively)." (PMID 27388918, 2016). "This is in line with previously published data which identified IL-22 producing cells in BAL from patients with pneumonia." (PMID 27388918, 2016). "IL-22 and IL-23 may play an important role in T. gondii RH strain pneumonia and may be the reason for the strong pathogenicity of T. gondii RH strain compared with T. gondii TGME49 strain infections." (PMID 36755348, 2023). "A recent study showed that insufficient levels of IL22 could be responsible for aberrant epithelial repair and adverse immune responses, leading to increased replication of the influenza virus and severe pneumonia." (PMID 37189778, 2023). "Treatment of RORγt diphtheria toxin receptor (DTR) newborn mice (Rorc Cre mice crossed with Rosa26-iDTR mice; RorγtiDTR) with DT diminished the number of ILC3s in the lungs and reduced IL-22 in bronchial lavage fluid (BAL), making them more susceptible to pneumonia." (PMID 34659248, 2021). "The behavior of ST258 in Il22−/− mice was contrary to that seen with infection with a more virulent laboratory strain where IL-22 was critical to the host defense in a mouse model of pneumonia." (PMID 32637365, 2020). "Furthermore, the administration of TLR5 agonist (flagellin) enhances the IL-22 production from group 3 ILCs during S. pneumoniae-induced pneumonia." (PMID 32849610, 2020). "p = 0.03), thereby demonstrating the protective role of IL-22 during PA acute pneumonia." (PMID 28887540, 2017). "However, Il22−/− mice in this study, were not more susceptible to pneumonia with ST258, suggesting that other innate immune factors are also important." (PMID 32637365, 2020). "IL-22 has been intensified because it was found to be a critical mediator of early mucosal defense against Gram-negative bacteria that cause intestinal disease and pneumonia in mouse models." (PMID 27031950, 2016). "Indeed, reduced concentrations of IL-22 as well as lower numbers of lung IL-22+ ILC3s in BAL were found in human newborns exposed to prolonged durations of antibiotics, thus contributing to increased susceptibility to pneumonia, which was reversed by transfer of commensal bacteria after birth." (PMID 34659248, 2021). "In addition, in a murine neonatal pneumonia model, IL-22-producing ILC3 were reduced in the lungs of offspring born to mothers on broad spectrum antibiotics from 5 days prior to delivery and offspring were also more susceptible to pneumonia induced by S. pneumoniae." (PMID 34151271, 2021). "During S. pneumoniae lung infection, the depletion of ILC3s protects the host from ALI due to inhibition of IL-22 and IL-17A production." (PMID 32849610, 2020). "In mice, pulmonary NK cells protect against K. pneumoniae-induced pneumonia via secreting IFN-γ and IL-22, which launch the bacterial growth-controlling interactions between alveolar macrophages and NK cells." (PMID 32849610, 2020). "Many studies have also described the importance of IL-22 and IL-17 produced by ILC3 as the key cytokines in bacterial-derived pneumonia." (PMID 32887435, 2020). "In the context of pneumococcal diseases, IL-22 can induce production of anti-microbial peptides such as beta defensin 2 which can inhibit the growth of the pneumococcus, and is also important for protection against different infections including pneumonia caused by Gram-negative bacteria." (PMID 26069966, 2015).
pneumonia (continued). "When the interleukin-25-induced group 2 innate lymphoid cells (ILC2) and interleukin-22 (IL-22)-producing group 3 innate lymphoid cells (ILC3) migrate to the lung, the host resistance to pneumonia and other inflammatory infections could be promoted." (PMID 35269538, 2022). "We found that high levels of IL-6, IFN-γ, and IL-2 and low levels of IL-5, IL-25, IL-17A, and IL-22 were found in the severe pneumonia group compared to the nonsevere pneumonia group." (PMID 34692846, 2021). "Recombinant IL-22 added to sputum from patients with Pseudomonas pneumonia was rapidly digested whereas sputum from patients with other forms of pneumonia failed to digest recombinant IL-22." (PMID 31443433, 2019). "Thus, in the setting of more chronic infection such as CF and COPD, the net effect on IL-22 and IFN-λ signaling pathways may not have as clear cut effects as can be illustrated in other models of acute pneumonia." (PMID 32637365, 2020).